S1PR5 (sphingosine-1-phosphate receptor 5)
Description:
Receptor for the lysosphingolipid sphingosine 1-phosphate (S1P). S1P is a bioactive lysophospholipid that elicits diverse physiological effect on most types of cells and tissues. Is coupled to both the G(i/0)alpha and G(12) subclass of heteromeric G proteins (By similarity). May play a regulatory role in the transformation of radial glial cells into astrocytes and may affect proliferative activity of these cells.
Synonyms: S1P5; EDG8; Edg-8; SPPR-1; SPPR-2
Tractability: Small molecule: an approved drug acts on it; a structure with a bound ligand is known; a high-quality ligand is known; it belongs to a druggable protein family. Antibody: its Gene Ontology location is reachable by antibodies, with high confidence; UniProt places it where antibodies can reach, with medium confidence; UniProt predicts a signal peptide or a membrane-spanning region. PROTAC: a small molecule that binds it is known.
Target class: EDG receptor; Family A G protein-coupled receptor; Lipid-like ligand receptor (family A GPCR); Membrane receptor; Small molecule receptor (family A GPCR)
Gene: Protein-coding gene on chromosome 19 (10,512,742 to 10,517,931, reverse strand). Ensembl gene ENSG00000180739.
Subcellular location: Cell membrane
Pathways (Reactome):
Signal Transduction: G alpha (i) signalling events; Lysosphingolipid and LPA receptors
Gene Ontology:
Molecular function: protein binding; G protein-coupled receptor activity; sphingosine-1-phosphate receptor activity
Biological process: adenylate cyclase-activating G protein-coupled receptor signaling pathway; G protein-coupled receptor signaling pathway; sphingosine-1-phosphate receptor signaling pathway
Cellular component: cytoplasm; plasma membrane; membrane; presynapse
Genetic constraint (gnomAD): Missense variants: 486 observed, 477.34 expected, observed/expected ratio (o/e) 1.02, 90% interval 0.94 to 1.1. Synonymous variants: 268 observed, 239.95 expected, observed/expected ratio (o/e) 1.12, 90% interval 1.01 to 1.24.
Homologues: Orthologues: macaque S1PR5 (95% identical), rabbit S1PR5 (89% identical), pig S1PR5 (86% identical), rat S1pr5 (86% identical), dog S1PR5 (86% identical), mouse S1pr5 (85% identical), tropical clawed frog s1pr5 (48% identical), zebrafish s1pr5a (47% identical), zebrafish s1pr5b (45% identical). Paralogues in human: S1PR1 (43% identical), S1PR2 (40% identical), S1PR3 (39% identical), S1PR4 (36% identical), LPAR2 (29% identical), LPAR1 (27% identical), GPR3 (25% identical), GPR6 (25% identical), LPAR3 (25% identical), GPR12 (24% identical), CNR1 (22% identical), CNR2 (21% identical), and 6 more.